USP7 (ubiquitin specific peptidase 7)
Diseases named in the same sentence as USP7 in open-access papers (continued):
Sharing a sentence is not in itself a finding about the gene and the disease.
tumor (continued). "The results indicated that overexpression of SNAI2 significantly promoted tumor growth, while knockdown of USP7 markedly inhibited tumor growth." (PMID 38702792, 2024). "For example, inhibitors of USP7 can improve the effectiveness of immunotherapy by regulating tumor inflammatory responses." (PMID 39767641, 2024). "An in-depth exploration of the functions and mechanisms of USP7 will help us better understand the process of tumor inflammatory responses and provide new ideas and methods for tumor treatment." (PMID 39767641, 2024). "To evaluate the effect of USP7 on OS growth in vivo, we examined knockout of USP7 (USP7 KO) using a tumor-bearing model." (PMID 38467635, 2024). "Considering these results, we went on to evaluate the functional impact of USP7 inhibition on immune checkpoint response in vivo in a series of CT‐26 tumour models." (PMID 38602256, 2024). "USP7 can influence the development and progression of tumor inflammation by affecting the function and activity of immune cells." (PMID 39767641, 2024). "Tumor growth was assessed based on the weight and volume, revealing a significant inhibition of tumor growth in cases of YY1 or USP7 downregulation." (PMID 38769122, 2024). "Almac4, another crucial USP7 inhibitor, has been shown to reduce tumor cell membrane PD-L1 levels, weaken the interaction between PD-L1 and PD-1, thereby rendering GC cells more sensitive to T cell-mediated cytotoxicity." (PMID 39748950, 2024). "In vitro data presented above indicates that USP7 inhibition has a marked effect on fibroblast‐mediated angiogenesis and impacts tumour spheroid growth, and only in the presence of fibroblasts and activated immune cells." (PMID 38602256, 2024). "Collectively, USP7 promoted CC cell proliferation, migration, invasion, angiogenesis, and macrophage M2 polarization in vitro, as well as tumor growth in vivo by regulating MTDH." (PMID 38625581, 2024). "The subcutaneous stromal plug model in nude mice confirmed the role of SNAI2 in USP7-mediated tumor VM in vivo." (PMID 38702792, 2024). "In summary, the role and mechanism of USP7 in the tumor inflammatory response is a complex process involving multiple signaling pathways and molecular mechanisms." (PMID 39767641, 2024). "Treatment with USP7 inhibitor P5091 in the xenograft model showed similar tumor growth inhibition but had minimal effects on the mice’s body weight." (PMID 39406703, 2024). "Increased USP7 expression has been demonstrated in numerous tumor entities and overexpression of USP7 was shown to promote carcinogenesis and to impair successful therapy." (PMID 38672118, 2024). "In mouse models of Lewis lung carcinoma, USP7 inhibitors slowed tumor growth, increased M1 macrophages, and enhanced IFN-γ+ CD8+ T-cell tumor infiltration." (PMID 38474186, 2024). "Future research needs to further explore the specific role mechanism of USP7 in tumor initiation and development and develop more effective inhibitors of USP7 to improve the effectiveness of tumor treatment." (PMID 39767641, 2024). "USP7 inhibitors upregulated the expression of PD-L1 in tumors, while inhibiting PD-1 had an effective anti-tumor activity." (PMID 38638430, 2024). "The rapid growth and proliferation of tumor cells require a large amount of energy and material support, and USP7 can create favorable conditions for the growth of tumor cells by affecting the associated metabolic pathways." (PMID 39767641, 2024).
tumor (continued). "Studies have shown that USP7 is highly expressed in M2-type macrophages, and its inhibition can promote the transition from M2 to M1 type, thereby enhancing the anti-tumor immune response." (PMID 39767641, 2024). "Further research revealed that USP7 can assist tumor cells in immune evasion by increasing the expression of PD-L1 protein." (PMID 39315102, 2024). "One of the best-studied deubiquitinating enzymes is USP7, playing an essential role in various cellular processes, such as DNA damage recognition and repair, immune response, epigenetics, tumor development and proliferation." (PMID 38672118, 2024). "The A11 peptide derived from ANXA1 competitively binds to PD-L1, inhibiting USP7-mediated deubiquitination of PD-L1 and promoting its degradation in various tumor cells." (PMID 39223632, 2024). "As a result, the role and mechanisms of USP7 in tumor inflammation have become a focal point of recent research." (PMID 39767641, 2024). "Overall, describing the role and mechanism of USP7 in the tumor inflammatory response is of great importance for elucidating the regulatory mechanism of tumor inflammation and developing new therapeutic strategies." (PMID 39767641, 2024). "The clinical data analysis with various public databases and CRC tumor tissues confirmed the high expression levels of USP7 and YY1 in CRC, along with a positive correlation between them." (PMID 38769122, 2024). "Engineered RMPs are then constructed that comprise: 1) the RMP carrier that targets and reprograms M2Φ; 2) a genetically expressed SR‐B1‐targeting peptide for improved BBB permeability; and 3) a USP7 inhibitor to kill tumor cells and reprogram M2Φ." (PMID 36698296, 2023). "Elevated USP7 expression is directly correlated with tumor aggressiveness and poor prognosis for many tumors, including NB." (PMID 37762082, 2023). "Treatment with CM from macrophages effectively reduced tumor volume and weight, which was more obvious when treatment with CM from USP7-overexpressed macrophages." (PMID 38129408, 2023). "Administration of USP7 inhibitor P5091 (25 mg/kg) has been found to decrease the growth rate of tumor in vivo." (PMID 37081042, 2023). "In BC, combination of the USP7 inhibitor with the trastuzumab weakened tumor growth in the xenografts model from a HER2-positive BC patient." (PMID 37658402, 2023). "Almac4 as another critical USP7 inhibitor, has been demonstrated to decrease tumor cell membrane PD-L1 levels, to attenuate the interaction between PD-L1 and PD-1, then making GC cells more sensitive to cytotoxicity mediated by T cells." (PMID 37658402, 2023). "TAM polarization towards proinflammatory M1 macrophages is induced by USP7 inhibition, enhancing anti-tumor immune responses." (PMID 37658402, 2023). "USP7 knockdown PLC-PRF-5 cells (using shUSP7 vector) were transplanted into BALB/c nude mice to establish xenograft tumor models and investigate the effect of USP7 on HCC progression in vivo." (PMID 37408047, 2023). "USP7 has been documented to play crucial roles in tumor development via modulating the stability and function of specific proteins." (PMID 38129408, 2023). "Comprehensive analyses of three different Apc-deletion mouse models show that loss of Usp7 significantly reduces crypt hyperproliferation, WNT activation, and tumor development in Apc-deficient intestine." (PMID 36669491, 2023). "USP7 exerts a variety of effects in DNA repair, apoptosis, and tumor metastasis which largely depends on the distinct functions of protein substrates." (PMID 37888853, 2023).
tumor (continued). "Instead, depletion of TRIM24 in macrophages promoted tumor growth, and also reversed the inhibitory effect of USP7 overexpression." (PMID 38129408, 2023). "Ubiquitin specific protease 7 (USP7) is a DUB that has been shown to play critical roles in regulating numerous proteins involved in tumor suppression, DNA repair, immune response, and epigenetic modulation." (PMID 37762082, 2023). "Recent studies reported that USP7 acts as a co-activator in tumor initiation by stabilizing Axin and hnRNPA1." (PMID 36878903, 2023). "USP7 is an extremely profitable target because it regulates the stability of several substrates that participate in control of tumor immune processes." (PMID 37658402, 2023). "HAUSP (USP7) deubiquitinates HIF-1α to induce tumor epithelial–mesenchymal transition and metastasis." (PMID 37190313, 2023). "It is also worth noting that genetic deletion of Usp7 in vivo displays a stronger effect of tumor suppression than the treatment of the USP7 inhibitor in PDOs." (PMID 36669491, 2023). "Comparison of bone marrow-resident tumor cells versus CTCs from this model identified protein ubiquitination as an important regulatory pathway in tumor cells, as inhibition of a specific deubiquitinating enzyme USP7 decreased systemic micrometastases." (PMID 37591867, 2023). "Previously, we have shown that the expression of the de‐ubiquitination enzyme USP7, an oncogene in the subcutaneous Lewis tumor model, is much higher in M2Ф than in M1Ф." (PMID 36698296, 2023). "Comparison of Apcmin and ApcminUsp7 cKO mice showed that Usp7 deletion significantly reduced tumor numbers at 4 months of age." (PMID 36669491, 2023). "Inhibition of USP7 by its inhibitors impedes the activity of Treg cells, enhances polarization of tumor-related macrophages in tumor cells." (PMID 37215134, 2023). "To further elucidate the regulation of USP7 on SAMHD1 protein stability, we next explored the effect of USP7-SAMHD1 axis on tumor cell survival under genotoxic insults." (PMID 37081042, 2023). "More important, USP7 inhibition was capable of potentiating the efficacy exhibited by the adenovirus-based tumor vaccine and the anti-PD-1 monoclonal antibody therapy in mice with TC1 lung tumor." (PMID 37658402, 2023). "On the other hand, Usp7 depletion in Lgr5 EGFP-IREScreApcfl/fl tumor model showed clear survival advantage, indicating that USP7 is an effective target for sporadic CRC." (PMID 36669491, 2023). "For all these reasons, USP-7 is a marker of tumor prognosis and a potential target for anti-tumor therapy." (PMID 37298148, 2023). "Elevated expression of USP7 has been observed in MM, and inhibition of USP7 can antagonize proliferation and induce cell death, thus representing a potential anti-tumor strategy." (PMID 36771100, 2023). "USP7 is a DUB that has been linked to a number of tumour-suppressor genes and proto-oncogenes, indicating its importance in tumour biology and progression." (PMID 37667522, 2023). "We have demonstrated that high expression of USP7 is associated with poor prognosis in children with NB and with other biological features of poor prognosis such as MYCN amplification and increased tumor stage." (PMID 37762082, 2023). "Although USP7 inhibitors combined with RMPs can effectively kill tumor cells in vitro, the number of RMPs produced by this system that can reach the CNS is limited." (PMID 36698296, 2023). "The enzyme ubiquitin‐specific protease 7 (USP7), which simultaneously regulates tumor growth and reprograms M2 macrophages (M2Φ), is found to be expressed in BRM." (PMID 36698296, 2023).
tumor (continued). "Another USP7 inhibitor Almac4 was shown to decrease PD-L1 levels in several tumor cell lines in a dose-dependent manner." (PMID 36428632, 2022). "To substantiate the pro-tumorigenic roles of USP7, we further exploited an HNSCC xenograft model and found that USP7 knockdown reduced tumor growth in vivo, accompanied by diminished TAZ and Ki-67 expression in samples." (PMID 35931679, 2022). "When evaluated in mice with Lewis lung carcinoma, USP7 inhibitor P5091 slowed tumor growth and promoted the infiltration of M1 macrophages and IFN-γ-expressing CD8+ T cells." (PMID 36428632, 2022). "The administration of USP7 inhibitors was also found to potentiate the efficacy of adenovirus-based tumor vaccine therapy." (PMID 36428632, 2022). "Our findings reinforced that USP7 was a novel viable therapeutic target for HNSCC as genetic depletion or pharmacological inhibition of USP7 resulted in reduced tumor growth in vivo likely in part via TAZ inhibition." (PMID 35931679, 2022). "USP7 is a deubiquitinase that regulates many diverse cellular processes, including tumor suppression." (PMID 35163049, 2022). "USP7 inhibitors increase PD-L1 levels, which renders tumor cells more amenable to anti-PD-1 therapy." (PMID 36428632, 2022). "High levels of USP7 are often found in HCC tissues and are associated with tumor growth and invasion, leading to poor overall survival." (PMID 35505392, 2022). "Pharmacological inhibition of USP7 significantly suppressed tumor growth in both xenograft and PDX models." (PMID 35931679, 2022). "USP7 was shown to deubiquitinate and stabilize the ERα subunit, promoting cell proliferation and tumor growth in ER-positive BC by inhibiting cell cycle arrest and apoptosis." (PMID 36291159, 2022). "Next, 3D spheroid model to further investigate the function of FEN1/USP7 axis in tumor growth and invasion." (PMID 35173534, 2022). "As for the anti-tumor mechanisms of PTL, existing evidences have shown that it can directly suppress NF-κB pathway and deubiquitinase USP7 activated abnormally in cancer cells and tumor stem cells." (PMID 36353537, 2022). "Increased levels of USP7 were shown to enhance tumor progression by modulating the immunosuppressive functions of Forkhead box P3 (Foxp3)+ T-regulatory (Treg) cells." (PMID 36428632, 2022). "The results of this study show that targeting USP7 can modulate the immunosuppressive effects within the tumor microenvironment and improve the efficiency of lung cancer immunotherapy." (PMID 36428632, 2022). "USP7 inhibition contributed to TAMs polarization into proinflammatory M1 macrophages and promoted the local anti-tumor immune response in TME in vivo, while also inducing systemic adaptive anti-tumor immunity." (PMID 36428632, 2022). "USP7 mRNA was aberrantly upregulated in HNSCC as compared to its non-tumor counterparts in two independent cohorts (TCGA-HNSC OSCC samples subset, named TCGA-OSCC and GSE25093)." (PMID 35931679, 2022). "On Day 16, the tumor volumes of mice orthotopically injected with USP7-silencing cell lines mice began to decline in comparison with control mice, even though the tumors of MDA-MB-231-DoxR and MDA-MB-231-PtxR xenograft models had different growth rates." (PMID 36291159, 2022). "USP7 inhibition stabilizes Foxp3, reduces Treg immunosuppression, and enables immune-mediated tumor suppression." (PMID 36428632, 2022). "Here, we summarize the recent advances in our understanding of how USP7 inhibitors influence the anti-tumor immune response in vivo." (PMID 36428632, 2022).
tumor (continued). "USP7 suppression impairs PD-L1/PD-1 interaction and enhances the cytotoxic reaction of T cells and the anti-tumor immune response." (PMID 35163049, 2022). "Positive nuclear staining of USP7 was detected in HNSCC samples while much less positive staining was observed in non-tumor oral mucosa." (PMID 35931679, 2022). "USP7 is involved in tumor metastasis through deubiquitination and localization of PTEN, which results in the inactivation of PTEN." (PMID 34869041, 2021). "USP7 is closely related to the clinical pathological features, such as tumor histological differentiation and lymph node metastasis." (PMID 34812471, 2021). "The knockdown of USP7, hnRNPA1, or lncFERO in GC cells relatively suppressed tumor growth in the saline groups, but remarkably increased chemosensitivity in the cisplatin groups." (PMID 34845198, 2021). "In agreement with previous reports of tumor suppression by targeting USP7, inactivation of USP7 also impaired the tumor progression of A549 cells in the xenograft mouse model." (PMID 34580281, 2021). "They showed potent inhibition with high selectivity for USP7 and proved capable of inducing tumor cell death." (PMID 34203106, 2021). "Knocking down of USP7 in tumor cells not only suppressed HSC3 cells proliferation, migration and invasion, but also promoted cell apoptosis." (PMID 34812471, 2021). "In order to illuminate the real roles of USP7 in carcinogenesis, it is requisite to further investigate the dual effects of USP7 in tumor regulation." (PMID 34869041, 2021). "Here is a summary of the mechanisms of USP7 for effecting tumor initiation and progression through interaction with its downstream proteins, as detailed below." (PMID 34869041, 2021). "In other words, USP7 displays tumor-promoting and/or -suppressive functions under different conditions." (PMID 34869041, 2021). "This theory’s generality is also manifested in the fact that targeting USP7 can help enhance tumor response to multiple therapeutic strategies, including traditional chemotherapy, molecular targeted therapy, immunotherapy, and radiation therapy." (PMID 33967786, 2021). "Conversely, USP7 knockdown results in the instability of Foxp3, which subsequently impairs the immunosuppressive function of Treg, and promotes tumor suppression mediated by the immune system." (PMID 34869041, 2021). "USP7 expression is not only closely related to tumor cell proliferation and invasion, but also affects some critical signaling pathways." (PMID 34812471, 2021). "This section further summarized and arranged the substrate proteins regulated by USP7 involved anti-tumor therapies resistance." (PMID 33967786, 2021). "We also confirmed that USP7 acts as tumour suppressor in RCC cells, as demonstrated that cells with USP7 knockdown exhibited increased proliferation." (PMID 33544460, 2021).